AREG (amphiregulin)
Diseases named in the same sentence as AREG in open-access papers (continued):
Sharing a sentence is not in itself a finding about the gene and the disease.
influenza (27 papers, 2013 to 2025). An acute viral infection of the respiratory tract, occurring in isolated cases, in epidemics, or in pandemics; it is caused by serologically different strains of viruses (influenzaviruses) designated A, B, and C, has a 3-day incubation period, and usually lasts for 3 to 10 days. "ILC2s have been directly implicated in influenza-induced alveolar repair due to their production of amphiregulin and Arginase-140,41,70." (PMID 32963227, 2020). "If sex differences in the pathogenesis of influenza are caused by differential production of AREG, then deletion of Areg should eliminate sex differences in disease." (PMID 30012205, 2018). "Mice lacking AREG specifically in Tregs show increased mortality following influenza infection and extensive lung damage, highlighting the critical role of Tregs in AREG-mediated tissue repair." (PMID 40948794, 2025). "Airway ILCs have been reported to protect against influenza-induced lung damage, including epithelial integrity and airway remodeling, in response to influenza infection, which is mediated by IL-33 and AREG." (PMID 38684766, 2024). "Role of Hypercytokinemia/hyperchemokinemia in the Pathogenesis of Influenza pathway was found to be significantly upregulated in the severe group’s monocytes with DEGs of AREG, CCL3, CCL4, CXCL8, IL1B, and ISG15 (coverage = 7% and p < 0.001)." (PMID 37495649, 2023). "Progesterone, with producing repair factors such as TGF-β and amphiregulin in the lungs, reduces alveolar penetration of proteins and decreases influenza infection mortality." (PMID 34912332, 2021). "Amphiregulin, a marker of alveolar stretch, has been found elevated in experimental influenza pneumonia, and was higher in BIVENTHigh-Effort compared to PSV and BIVENTLow-Effort." (PMID 33577592, 2021). "Such examples include the role of amphiregulin in modulation of dextran sulfate induced intestinal inflammation and influenza infection where ILC2-derived amphiregulin was critical in restoring barrier integrity and mediating airway remodeling." (PMID 32793230, 2020). "In comparison, IL-17A-producing γδT cells in the lung can upregulate expression of IL-33 and amphiregulin, thereby promoting lung repair following influenza infection." (PMID 31337278, 2019). "Strikingly, ILC2-derived amphiregulin is involved in tissue repair and remodeling suggesting that ILC2s are capable of lung tissue homeostasis during influenza." (PMID 31612153, 2019). "The authors found a similar correlation of IL-17, IL-33, and amphiregulin in the nasal wash of human infants infected with influenza, identifying an axis of IL-17 production from γδ-T cells in the production of IL-33 for ILC2 repair responses in the lung." (PMID 31354734, 2019). "ILC2s have been best studied in relation to influenza, due to their ability to mediate tissue repair following Influenza infection via the production of amphiregulin." (PMID 30761149, 2019). "Intriguingly, IL-17 production from γδ-T cells was shown during neonatal influenza to augment IL-33 production from the mucosa, generating a type 2 response and the production of amphiregulin by ILC2s." (PMID 31354734, 2019). "Amphiregulin production by regulatory TRM cells was also shown to prevent excessive host pathology following influenza infection, by inducing epithelium proliferation and repair after viral clearance." (PMID 30386342, 2018). "In these cases of both Th2 lung fibrosis and post influenza tissue repair, amphiregulin production by distinct TRM subsets promotes distinct types of local immunity." (PMID 30386342, 2018). "Taken together, these data show that elevated levels of testosterone and AREG, either independently or in combination, improve resilience (i.e., repair and recovery of damaged tissue) and contribute to better influenza outcomes in males compared with females." (PMID 30012205, 2018). "Pulmonary ILC2 secretion of amphiregulin restores the integrity of the airway epithelium following influenza infection." (PMID 29261670, 2017).
influenza (continued). "ILC2s have been shown to promote tissue repair and lung homeostasis during influenza infection by secretion of amphiregulin." (PMID 26965110, 2016). "Similarly, in models of influenza-induced lung damage, Treg-specific deletion of AREG impairs tissue repair despite a normal antiviral immune response, indicating that the role of AREG is specifically regenerative." (PMID 40948794, 2025). "This evidence may suggest that the IL-17/IL-33/amphiregulin axis may serve as a potential therapeutic target that is specifically important in cases of influenza infection in neonates." (PMID 31337278, 2019). "It will be interesting to know what cells produce amphiregulin and whether it may be a biomarker to predict disease severity in human influenza patients." (PMID 27088501, 2016). "A more direct illustration that amphiregulin is important in tissue repair after infection is evident in mouse models of influenza-associated lung inflammation with or without secondary bacterial pneumonia in whom treatment with amphiregulin restored lung function and/or increased survival." (PMID 38195661, 2024). "Given findings showing that amphiregulin promotes epithelial cell repair and tissue remodeling in models of influenza or dextran sulfate sodium (DSS)-induced colitis, it may be that these cells instead promote enhanced tissue repair at later timepoints during Hulk infection." (PMID 34237106, 2021). "For example, the mouse-adapted influenza model PR8 induces a greater number of CD90+CD25+ ILC2s, which are essential in the amphiregulin-dependent reparative process following exposure to this cytopathic virus." (PMID 36052086, 2022). "In particular, ILC1 induces the cytolysis of influenza-infected cells and ILC2 is trafficked into lung upon influenza infection and becomes activated, releasing amphiregulin (Areg), which contributes to repairing the damaged tissue." (PMID 33183352, 2020). "AREG also stimulates the proliferation and differentiation of AT2 cells, as exemplified by Treg-derived AREG stimulation of a population of Col14a1+EGFR+ mesenchymal cells, which mediates the regeneration of AT2 cells during influenza-induced lung injury in mice." (PMID 40114929, 2025). "Treg cell-derived amphiregulin has also been shown to be critical for preventing lung tissue damage during acute influenza infection, independent of suppressive function." (PMID 36159872, 2022). "Classical monocytes from patients with CAP-flu displayed upregulation of a variety of genes involved in pro-inflammatory processes, such as EGR-1, FKB5, and AREG." (PMID 34424199, 2021).
pulmonary fibrosis (27 papers, 2014 to 2025). Chronic progressive interstitial lung disorder characterized by the replacement of the lung tissue by connective tissue, leading to progressive dyspnea, respiratory failure, or right heart failure. "The identification of AREG as a key mediator in pulmonary fibrosis has prompted the development of targeted therapeutic strategies aimed at selectively inhibiting AREG signaling while avoiding the broad toxicities associated with general EGFR or TGF-β pathway inhibition." (PMID 40725192, 2025). "Indeed, both circulating and pulmonary COVID-19 NK cells expressed high levels of AREG (encoding for amphiregulin), an epidermal growth factor receptor ligand involved in pulmonary fibrosis." (PMID 35844604, 2022). "This indicated that AREG was associated with lung fibrosis and the alveolar EMT in asthmatic mice." (PMID 36578010, 2022). "Group II ILCs specifically, secrete the cytokines IL-5, IL-13, IL-9, amphiregulin, and low quantities of IL-4 and have been linked to several lung-associated conditions including pathogen infections (viruses and helminths), asthma, and pulmonary fibrosis." (PMID 30413212, 2018). "These investigations showed an important regulatory activity of AREG in the pathogenesis of TGF-β1-induced pulmonary fibrosis." (PMID 40868999, 2025). "The profibrotic effects of AREG in lung fibrosis are mediated through multiple cellular sources and signaling pathways." (PMID 40725192, 2025). "The binding of the EGFR ligand amphiregulin was shown to be essential for TGFβ-dependent pulmonary fibrosis in mouse models." (PMID 35967296, 2022). "For example, AREG expression was significantly enhanced in acute lung injury induced by lipopolysaccharide and pulmonary fibrosis induced by bleomycin." (PMID 35996142, 2022). "To identify the role of AREG in lung fibrosis in mice with OVA-induced asthma, we observed thickened interstitial alveoli and airway remodeling in sections of lung tissues from OVA-challenged mice." (PMID 36578010, 2022). "AREG expression on DCs has been reported to trigger tumorigenesis in response to ATP and promote pulmonary fibrosis in CD11c+ bone marrow DCs; however, previous studies have not addressed its role in allergic responses." (PMID 33207814, 2020). "Inhibition of AREG or EGFR in TGF-β1-stimulated lung fibroblasts diminished AREG-dependent fibroblast proliferation, expression of α-smooth muscle actin and collagen, strongly suggesting a role of EGFR/ADAM17/AREG signaling in pulmonary fibrosis in vivo." (PMID 29540993, 2018). "AREG also participates in pulmonary fibrosis by modulation of TGF-α, and EGFR inhibitors can decrease pulmonary fibrosis." (PMID 24788984, 2014). "Emerging evidence indicates that AREG plays a crucial role in the pathogenesis of lung fibrosis and may serve as a prognostic biomarker." (PMID 40725192, 2025). "Similarly, AREG-targeting siRNA significantly reduced pulmonary fibrosis in TGF-β transgenic mice, with decreased collagen deposition and preserved lung architecture." (PMID 40725192, 2025). "Among these mediators, AREG has, in recent years, gained great appeal as a molecular target whose modulation could represent an alternative and effective method to block pulmonary fibrosis." (PMID 40868999, 2025). "The therapeutic effect of SAMiRNA-AREG, reported in mouse models and characterized by the stable silencing of the AREG gene, resulting in a reduction in the side effects of conventional siRNA treatment of pulmonary fibrosis, has also been evaluated in renal fibrosis." (PMID 40868999, 2025). "Moreover, connections between IL-5 and AREG have been reported in the severe asthma and lung fibrosis." (PMID 38831884, 2024). "We hypothesized that proteins previously shown to be elevated in patients with pulmonary fibrosis (Amphiregulin, MMP-9, MMP-7, P-selectin, S100A12, and CXCL12) would be elevated in patients who develop fibroproliferative ARDS." (PMID 39106254, 2024).
pulmonary fibrosis (continued). "Besides its “bad” role in lung fibrosis, AREG was also found to contribute to the restoration of tissue homeostasis after acute lung injury driven by infection." (PMID 35326439, 2022). "Given prior paradoxical links of Amphiregulin to fibrosis, we sought to delineate the contributions of Amphiregulin in lung fibrosis in the context of PH." (PMID 35732465, 2022). "AREG is an epidermal growth factor ligand which plays an important role in tissue repair and pulmonary fibrosis and its increased expression in patients with severe COVID-19 disease has been negatively correlated with genes associated with cytotoxic NK cell functions." (PMID 34824360, 2021). "Previously, we reported that the AREG-targeting Self-Assembled-Micelle inhibitory RNA (SAMiRNA-AREG) alleviated fibrosis by stably silencing the AREG gene, and reduced the side effects of conventional siRNA treatment of pulmonary fibrosis." (PMID 33500443, 2021). "Infected alveolar epithelial cells are thought to be the primary source of these mediators, exacerbating pulmonary inflammation and immune dysfunction, and sustained amphiregulin activation may contribute to lung fibrosis and pulmonary symptoms of persistent lung inflammation." (PMID 40851359, 2025). "In addition, Amphiregulin has been shown to increase cardiac fibrosis and aggravate cardiac dysfunction in a mouse model of myocardial infarction, and promote fibroblast activation in pulmonary fibrosis." (PMID 35732465, 2022). "Furthermore, AREG plays an essential role in pathogenesis of TGF-beta-induced pulmonary fibrosis." (PMID 34442026, 2021). "Notably, CD4+ T cells in cluster T9 expressed high levels of KLF6 that positively regulates the expression of TGFβ and molecules in the TGFβ pathway, AREG (amphiregulin) that is involved in pulmonary fibrosis, and CXCR4 that may promote T-cell migration to the lung." (PMID 35558069, 2022). "Our groups previously demonstrated that SAMiRNA-AREG efficiently knocked down AREG mRNA and protein levels, and fibrotic markers and α-SMA were downregulated by inhibiting AREG in TGF-β transgenic mice and the bleomycin-induced pulmonary fibrosis model." (PMID 33500443, 2021). "Interestingly increased levels of amphiregulin are also found during coronavirus (SARS-CoV) infection, where many survivors develop pulmonary fibrosis." (PMID 35922425, 2022). "Consistent with these in vitro findings, AREG expression was markedly increased in the lungs of dox-CC10-TGF-β1 overexpressing mice and administration of AREG siRNA or AG1478 reduced collagen content and attenuated lung fibrosis in these animals." (PMID 35326439, 2022). "ADAM17 is involved in a variety of inflammatory processes, including activation and release of TNF, modulation of neuregulins such as AREG, and being a necessary cofactor for IL6 trans-signaling, which has been shown to promote pulmonary fibrosis in bleomycin injury." (PMID 36291184, 2022). "Severe acute respiratory syndrome coronavirus (SARS-CoV) infection leads to the upregulation of EGFR ligands such as heparin-binding EGF-like growth factor (HB-EGF) and amphiregulin (AREG), and overactivation of EGFR leads to severe lung damage and pulmonary fibrosis." (PMID 34517756, 2021). "Therefore, it seems plausible that both AREG and CTGF may be required to optimally activate the EGFR/TGF-β-mediated pulmonary fibrosis pathways." (PMID 40868999, 2025). "In addition, based on the potentially pivotal role that dysregulation of AREG and EGFR signaling may play in pulmonary fibrosis pathogenesis, AREG could be a potential therapeutic target for IIM-related ILD." (PMID 34442026, 2021). "Our previous studies demonstrate upregulation of multiple growth factors including TGFβ, IL-6, IL-13, amphiregulin and epiregulin in distinct mesenchymal cell subsets such as fibrocytes, lung resident fibroblasts and WT1-positive myofibroblasts during TGFα-induced pulmonary fibrosis." (PMID 31156440, 2019).
COVID-19 (26 papers, 2020 to 2025). A disease caused by infection with severe acute respiratory syndrome coronavirus 2. "While it has been previously documented that TNF-α and IFN-γ are associated with mortality during COVID-19, a novel finding from our study is the association of amphiregulin with VFDs and development of fibroproliferation." (PMID 39106254, 2024). "Our findings support a prior study that identified amphiregulin as a cytokine associated with disease severity in COVID-19 in a proteomics screen." (PMID 39106254, 2024). "Elastic net analysis demonstrated that specific proteins, including amphiregulin, effectively predict COVID-19 severity from sera at admission (samples drawn within 96 h of admission), with a test area under the curve of 0.84." (PMID 41166719, 2025). "Among these, AREG has been identified previously as a potential marker of COVID-19 severity, corroborating existing literature." (PMID 41166719, 2025). "Although we describe amphiregulin in a small cohort of patients with severe COVID-19, our findings add to the growing body of evidence that amphiregulin is important in both appropriate and aberrant tissue repair mechanisms in viral ARDS." (PMID 39106254, 2024). "The MDDC_AREG subpopulation was specifically enriched in both ARDS groups, and high expression of the pro-fibrotic gene AREG acts as a distinct marker for monocytes in severe COVID-19 cases." (PMID 38238762, 2024). "In the studies above, the number of amphiregulin-producing ILCs in the course of SARS-CoV-2 infection was found to be higher in women than in men, and those hospitalized with COVID-19 had a lower percentage of amphiregulin-producing ILCs than controls." (PMID 38391948, 2024). "For example, in contrast to the transcriptional changes induced by low-dose IL-2 in T1D patients, we observed a downregulation of CISH and an upregulation of AREG in COVID-19 patients during acute infection, across multiple immune cell types." (PMID 37700317, 2023). "As a result, the significant increase of interferon-I response and amphiregulin expression levels was found in patients with COVID-19 comparing to the healthy controls." (PMID 37795081, 2023). "Among controls, the percentage of ILCs that produced amphiregulin was higher in females than in males, and people hospitalized with COVID-19 had a lower percentage of ILCs that produced amphiregulin than did controls." (PMID 35275061, 2022). "The plasma IL-6 levels of the patients with COVID-19 on day 1 and the sepsis patients on days 1 and 2-3, and the plasma amphiregulin levels of the sepsis patients on day 1, were significantly higher than those of the healthy controls." (PMID 35095877, 2021). "Plasma concentrations of amphiregulin, an epidermal growth factor produced by damaged epithelial cells that promotes lung repair, were elevated in patients with COVID-19." (PMID 34648357, 2021). "Moreover, the patients with comorbidities showed the upregulation of well-established COVID-19-related inflammatory markers, such as AREG, an IL-18-induced cytokine, which is involved in restoring tissue integrity." (PMID 37047248, 2023). "In particular, we found an association between plasma proteins elevated in severe COVID-19, such as HGF, AREG, CKAP4, S100A12, NCF2, ITGB6, and a subpopulation of monocytes with lower expression of CD86 and HLA-DR, which are characteristics of myeloid-derived suppressor-like cells." (PMID 36829233, 2023). "Moreover, some regulatory and tissue repair-associated genes (CD163, IL1R2, AREG, HAVCR2 (encoding TIM-3), and its ligand LGALS9) and pathways (TIM-3/Gal-9 pathway) were found up-regulated in progressive COVID-19 patients." (PMID 37795081, 2023). "Higher levels of several of these proteins were inversely correlated with viral load, including the cytosolic RNA sensor RIG-I (gene symbol DDX58), chemokines (CCL20 and CCL25), and other proteins (Keratin 19 [KRT19], amphiregulin [AREG]) previously shown to be upregulated in COVID-19 patients." (PMID 36239699, 2022).